INS (insulin)
Diseases named in the same sentence as INS in open-access papers (continued):
Sharing a sentence is not in itself a finding about the gene and the disease.
diabetes (continued). "Diabetes mellitus is a chronic non-communicable disease due to either genetic or acquired deficiency in insulin production (type 1 diabetes mellitus: T1DM), or a lack of action of this hormone (type 2 diabetes mellitus: T2DM)." (PMID 30186783, 2018). "The well-known disease related to the dysregulation of insulin is diabetes." (PMID 30774812, 2018). "Using CGMS, we further identified that young-onset type 2 diabetes, defined as age less than 40-yrs old, received a metformin combination with CSII therapy which required significantly lower insulin doses to maintain glycemic control compared to the late onset diabetes patients." (PMID 29780415, 2018). "Comparatively better self-care score among tablet with a combined of insulin therapy in the present study could be these people might have a diabetes which was uncontrolled by mono-therapy (tablets or insulin alone)." (PMID 30409148, 2018). "Furthermore, mangiferin was shown to protect against diabetes and dyslipidemia in diabetic, insulin resistant rats by improving insulin sensitivity, modulating lipid profile and reverting adipokine levels to normal." (PMID 30563087, 2018). "Higher vaspin mRNA expression is correlated with type 2 diabetes mellitus, obesity and insulin resistance; this increment in vaspin serum levels leads to improvements in glucose metabolism and insulin sensitivity in visceral adipose tissue, but the main molecular mechanism of vaspin is unidentified." (PMID 29337850, 2018). "Interestingly, podocytes are insulin sensitive and have been shown to develop insulin resistance in animal models of diabetes." (PMID 29686650, 2018). "Combined therapy could then improve cardiac insulin sensitivity, anti-inflammatory, anti-apoptotic, anti-fibrotic effects during the subacute period of diabetes." (PMID 29959408, 2018). "Patients with diabetes needing titration of basal insulin have the option of self-titration." (PMID 29555621, 2018). "Optimized insulin dosing achieved through an insulin management service also may reduce overall drug costs by reducing the use of expensive diabetes medications." (PMID 32685571, 2018). "Prediction of insulin sensitivity by BMI and fasting plasma mannose levels was more accurate than the prediction by BMI alone, which may contribute to more precise estimation of insulin sensitivity in patients with diabetes." (PMID 30534205, 2018). "Such detailed information regarding glucose profiles may allow women with diabetes and clinicians to better target insulin delivery with the aim of optimising time in target range and decreasing adverse pregnancy outcomes." (PMID 29383544, 2018). "Indeed, compared to NPH, basal insulin analogues have been shown to reduce the incidence of hypoglycemia (especially nocturnal) and weight gain—two main adverse effects that may be associated with intensifying diabetes treatment, and are a concern for both patients and physicians." (PMID 29460260, 2018). "Conversely, individuals may start life with shorter than normal telomeres that then play a role in the disease progression of diabetes, contributing to impaired glucose management and insulin secretion." (PMID 30533028, 2018). "A group of patients with T2D, who had switched to IDeg from another basal insulin, reported HRQoL benefits which were attributed to both diabetes-specific improvements (feeling less burdened by day-to-day diabetes demands) and non-specific gains (greater energy)." (PMID 29720273, 2018). "In recipient mice, the resulting cells can produce human insulin to reverse diabetes." (PMID 30594258, 2018). "Nonetheless, the used model was streptozotocin-nicotinamide diabetes induced (insulin deficient model) rather than insulin resistant induced model." (PMID 29844959, 2018). "Moreover, men develop diabetes at a lower body mass index and are predestined to be more insulin-resistant." (PMID 30564194, 2018).
diabetes (continued). "Regardless of its underlying cause, diabetes mellitus is subdivided into three clinical stages: noninsulin requiring, insulin requiring for control, and insulin requiring for survival, the third of which corresponds to insulin deficiency." (PMID 30116734, 2018). "The PI3K/Akt signaling pathway plays a key role in insulin-stimulated GLUT4 glucose transporter translocation and impairments in this cascade lead to reduced insulin-induced glucose transport into muscle cells contributing to insulin resistance and type 2 diabetes mellitus (T2DM)." (PMID 29710819, 2018). "Hyperinsulinemia may in turn be driven by mTOR signaling, which suggests a state of pre-pre-pre-diabetes in which both glucose and insulin levels are normal." (PMID 30448823, 2018). "Increased insulin secretion in neonates and decreased insulin secretion in later life might explain the hypoglycemia and diabetes at various stages of the disease, but the mechanism of the differential aspects of the HNF4A defect on β-cell function is unclear." (PMID 30005691, 2018). "Our study was based on the assumption that insulin resistance in the central nervous system is, at least partly, responsible for hypogonadotropic hypogonadism observed in men with diabetes, and that intranasal insulin may restore insulin signaling." (PMID 30515210, 2018). "However, the pharmacologic options available for treating diabetes mellitus in humans usually have the opposite effect, with the aim of increasing insulin secretion from a failing pancreas, or augmenting insulin action." (PMID 29958298, 2018). "No study to date has examined whether exposure to experimental hyperglycemia (via infusion) or rapid normalization of hyperglycemia in diabetes patients (via insulin or sodium-glucose cotransport inhibitors drugs) can influence exercise adaptations." (PMID 30061841, 2018). "The percentages of people with any level of DR greater than ‘no apparent’ increased in expected ways when risk factors were considered; i.e., percentages were higher among patients with longer duration of diabetes and patients taking insulin alone or with oral medications." (PMID 29924846, 2018). "Mean duration of diabetes was 16.7 (±10.3) years, 33.6% were insulin users with a mean HbA1c of 7.38% (±1.13), 34.5% had a history of IHD, 14.7% a history of CVD, 2.6% were current smokers, 97% reported a diagnosis of hypertension or took regular hypertension medications, and 97% had dyslipidemia." (PMID 29899221, 2018). "Pancreatic islets destruction and cell death is major pathophysiologic abnormalities underling both type 1 diabetes (T1DM) and type 2 diabetes (T2DM), and absolute or relative defects of β cell insulin secretion are characterized by almost all forms of diabetes." (PMID 30552311, 2018). "In addition to insulin administration, successful management of diabetic ketoacidosis requires fluid resuscitation." (PMID 30473969, 2018). "There is also a need to understand the effect of foods and diets on beta-cell function, as the available evidence suggests moderate weight loss, as achieved in the diabetes prevention trials, improves insulin sensitivity but not beta-cell function." (PMID 30200572, 2018). "Moreover, the 1-year repeat revascularization rate was higher (HR 1.44, 95% CI 1.05–1.97) in insulin treated diabetes, primarily due to increased repeat revascularization procedures in the insulin-treated PCI group." (PMID 29402330, 2018). "Correct technique in insulin delivery is critical for optimal control of diabetes." (PMID 29508275, 2018). "Onset of exercise in individuals without diabetes is associated with decreased insulin secretion and increased glucagon secretion." (PMID 29720965, 2018). "Thus, RIP-directed miR-7a over-expression in β-cells leads to diabetes via β-cell dedifferentiation and impaired insulin secretion, while β-cell miR-7 KO increased GSIS and insulin exocytosis." (PMID 30551650, 2018).
diabetes (continued). "The rate at which insulin secretion by beta-cells diminishes in T2D is greater in youth (age 10–17 years) than in adults, which results in earlier and more aggressive development of diabetes-related complications." (PMID 30014302, 2018). "Increased concentrations of insulin, C-peptide and leptin have been associated with increased intra-abdominal fat, in both the short and long term, in Japanese-Americans without diabetes." (PMID 30555835, 2018). "Needle phobia in a subgroup of patients with diabetes, which often goes unrecognized or unreported, contributes to patient inertia and manifests as resistance to starting insulin injections even as T2D progresses from insulin resistance to total insulin deficiency." (PMID 29707584, 2018). "Use of jet injection, where insulin is administered at high velocity across the skin, instead of conventional pen administration has been shown to accelerate absorption of insulin aspart in healthy subjects and persons with diabetes." (PMID 30116732, 2018). "T2DM, namely non-insulin-dependent DM or adult-onset diabetes, is characterized by hyperlipidemia and hyperglycemia resulting from the insulin resistance in peripheral tissues or impaired insulin synthesis in the pancreas, and it has accounted for over 90% of diabetes patients." (PMID 30595798, 2018). "Another aspect of PPG is glycemic variability, which was associated with HbA1c in individuals with non-insulin-treated T2D, but not in individuals without diabetes." (PMID 29855488, 2018). "The insulinotropic activity of these Ficus deltoidea varieties suggests that they can potentially be developed as a new phytopharmaceutical agent for the management of diabetes mellitus potentially for escalation of insulin secretion from insulin producing cells." (PMID 30046337, 2018). "The study has shown statistically significant differences in mean visfatin concentrations between patients with diabetes mellitus type 2 treated with metformin and patients with diabetes mellitus type 2 treated with insulin, respectively (21.3 ng/ml, 28.4 ng/ml)." (PMID 29516012, 2018). "We suggest the potential use of BACE1 inhibitors to enhance insulin signaling during diabetes." (PMID 29610518, 2018). "As a result, the bioactivity of important metabolism regulating hormones, like insulin, could be further affected by protein glycation in diabetics." (PMID 30395577, 2018). "Therefore, the most relevant model of human obesity/diabetes is the high-fat diet-induced obese mice with elevated inflammation, insulin resistance, and glucose tolerance." (PMID 30054493, 2018). "Finally, in the study addressing the effect of FBS on mechanisms of tolDC-action in NOD mice, only GM-CSF and IL-10 generated tolDCs pulsed with 2 insulin B chain peptides prevented diabetes in NOD mice." (PMID 29503651, 2018). "The increased glycogen synthesis in the HGI model may be similar to the hepatic glycogenosis occurring in patients with type 2 diabetes mellitus who had concomitant presence of insulin and excess glucose." (PMID 30024975, 2018). "Our data suggested that the increased prevalence of diabetes in patients with low sKlotho level might be related to the regulatory roles of sKlotho in insulin/insulin-like growth factor-1 (IGF-1) signaling pathways." (PMID 29900135, 2018). "Activated AMPK inhibits anabolic processes which consume ATP, reduces inflammation, inhibits endothelial cell proliferation, stimulates mitochondrial biogenesis, and increases insulin sensitivity, making it an attractive pharmacological target for diabetes and cardiovascular pathologies." (PMID 30563079, 2018). "It is worth mentioning that most of the reasons could be demystified with proper diabetes education and with the new, easier-to-use and painless devices to deliver insulin and monitor blood glucose." (PMID 29636825, 2018). "Diabetes is a debilitating disease that affects the way the body uses or produces insulin." (PMID 30533325, 2018).
diabetes (continued). "Failure to recognize the role of insulin and unwillingness allow for long term usage in their wards as well as the respondents reluctance to adopt healthy life style modifications compound the treatment of the children with diabetes and foster poor outcome." (PMID 29986694, 2018). "These pIPCs were then given to NOD mice before the onset of clinical manifestations of T1D and compared with the group of mice that received MSCs differentiated into insulin-producing cells and controls to compare the efficacy of the two modalities to arrest diabetes in NOD mice." (PMID 28701182, 2017). "This is an important and growing sub-population as primary care clinicians are challenged to up-titrate medication, seek better control of diabetes symptoms and HbA1c, and to judge the overall risks and benefits, the alternatives and the optimal timing of commencement of insulin therapy." (PMID 28830436, 2017). "The exclusion of people with insulin treated diabetes from these programmes may limit further detailed study of this group." (PMID 28265893, 2017). "In clinical studies, triggering of diabetes mellitus in previously asthmatic patients resulted in an improvement in asthmatic symptoms; treatment of diabetic patients with insulin aggravated asthma, and similar results were observed in non-diabetic asthmatic patients receiving insulin." (PMID 28649241, 2017). "For example, the proportion of antihypertensive drug use among patients with hypertension increased from 21.9% in 1998 to 54.8% in 2007, and the proportion of insulin or oral hypoglycemic drug treatment among patients with diabetes increased from 29.7% in 1998 to 57.4% in 2007." (PMID 29228048, 2017). "The study patients had had diabetes for more than 5 years (mean duration of diabetes of 9.4 years), but only 29% were on insulin therapy, either in combination or as sole therapy, suggesting that the glucose-lowering treament may not have been intensified." (PMID 29191193, 2017). "Diabetes in rats was induced with the intraperitoneal injection of STZ, which selectively damaged the pancreatic beta cells, leading to cell death caused by the decrease in insulin and increase in blood glucose levels." (PMID 28367226, 2017). "Indeed, patients' response to insulin intensive therapy is quietly variable, mirroring the heterogeneity of diabetes." (PMID 28271075, 2017). "Likewise, any damage to the β cells, which produce insulin, will lead to persistent hyperglycaemia, the common characteristics of diabetes." (PMID 28064559, 2017). "However, there is controversy about the effectiveness of vitamin A, retinol and its carrier proteins, retinol binding protein (RBP) and transthyretin for treating diabetes since the effects on insulin secretion seem to be dependent on its metabolites." (PMID 28574454, 2017). "So, weight reduction occurs as a result of the progressive decline of insulin action in diabetes." (PMID 28348972, 2017). "Diabetes mellitus might influence survival of CRC patients due to insulin-stimulated growth of colorectal cancer cells or inadequate treatment of persons with concomitant disease." (PMID 28423026, 2017). "The data presented shows the relationship between pre-existing use of injectable insulin in women diagnosed with breast cancer and type 2 diabetes mellitus, the inflammatory C–C chemokine profiles at the time of breast cancer diagnosis, and subsequent cancer outcomes." (PMID 28289694, 2017). "The aim of this study was to examine the effect of a reduced carbohydrate diet that was moderately high in both protein and dietary fiber (HPHFib diet) on IS and insulin secretion, using the DISST method, in overweight and obese women at risk of diabetes, independently of weight loss." (PMID 29186908, 2017).
diabetes (continued). "Although some individuals diagnosed with diabetes are able to identify that increased blood glucose is a result of disease affecting the pancreas and insulin (16%, n = 3), a minority are able to correctly state signs and symptoms of high blood glucose or complications from diabetes (35%)." (PMID 28245810, 2017). "S-methyl L-cysteine from garlic and onion could treat and manage the diabetes; however S-allylcysteine might be stimulating the synthesis of insulin through circulating thyroid hormones." (PMID 28261311, 2017). "Furthermore, in humans, mutations in the EIF2AK3 gene, which encodes PERK, causes Wolcott–Rallison syndrome, which is characterized by permanent neonatal or early infancy diabetes because of impaired insulin secretion." (PMID 28208663, 2017). "Dysregulation of insulin secretion dynamics plays a role in diabetes development." (PMID 29118381, 2017). "As we were unable to distinguish between uncomplicated hyperglycaemia and the acute glycaemic emergencies (DKA and HHS), this group may have included people with reduced insulin sensitivity or ‘pre-diabetes’ as well as those with first presentation DKA or HHS." (PMID 28771639, 2017). "Research suggests that in-vivo modulation of the gut microbiome by specific probiotic microorganisms may improve insulin sensitivity and blood sugar management, preventing or delaying the development of type 2 diabetes mellitus." (PMID 28069054, 2017). "This dataset presents the relationship between baseline insulin secretagogues use in women diagnosed with breast cancer and type 2 diabetes mellitus, the T-helper 1 and 2 produced cytokine profiles at the time of breast cancer diagnosis, and subsequent cancer outcomes." (PMID 28280762, 2017). "Our results confirmed a link between insulin homeostasis and tau phosphorylation, which could, at least, contribute to co-morbidity between diabetes and AD." (PMID 28402338, 2017). "Diabetes is a predominant, usually life-long health condition commonly identified by an increased blood glucose level (hyperglycemia) arising in the wake of defects in insulin action and/or secretion." (PMID 29234684, 2017). "Type 2 diabetes mellitus (T2DM) is a chronic and common metabolic disease with a worldwide increase in prevalence, and is associated with severe syndrome and characterized with deficit in insulin production or sensitivity." (PMID 28634451, 2017). "The cKO mice showed significantly higher insulin sensitivity, represented by a high glucose infusion rate to maintain the euglycemia under insulin infusion, indicating that Ant2 liver cKO is protective against changes that are common in pre-diabetes." (PMID 28205519, 2017). "Impaired insulin action in muscles leads to insulin resistance and type 2 diabetes mellitus." (PMID 28991159, 2017). "In addition, Nrf2 activation improves insulin sensitivity in diabetes, abrogates diabetes and obesity in mice, and increases oxygen consumption and glucose uptake in skeletal muscle." (PMID 29271910, 2017). "With aging, insulin and glucagon contents did not significantly change in ND subjects but declined in T2D subjects, without association with the duration of diabetes or type of treatment." (PMID 28887444, 2017). "Excess circulating insulin, arising from insulin resistance in diabetes, may increase blood pressure by stimulating the sympathetic nervous system, acting as a growth factor, and/or increasing sodium reabsorption in the kidneys." (PMID 29299337, 2017). "The precise mechanism by which hnRNP F/K mediate insulin downregulation of renalNrf2 gene expression in diabetes remains unclear." (PMID 28324005, 2017). "Strict avoidance of hypoglycemia may partially restore awareness of hypoglycemia, however this is very challenging for insulin treated patients with diabetes to maintain long-term." (PMID 28993722, 2017).